IL17A (interleukin 17A)
Diseases named in the same sentence as IL17A in open-access papers (continued):
Sharing a sentence is not in itself a finding about the gene and the disease.
psoriasis (continued). "Thus, IL-36 signaling is also upregulated in two mouse models of IL-17A-driven psoriasis, which can subsequently be utilized to investigate anti-IL36R antibody treatment in IL-17A-driven psoriasis." (PMID 38162658, 2023). "In addition, AOA treatment significantly decreased the expression levels of Il17a, RAR related orphan receptor C (Rorc), and IL22 in ear skin of the psoriasis-like mouse model." (PMID 37649889, 2023). "Obviously, IL-17A is not the only requirement for psoriasis pathogenesis, for example IL-17F can also bind IL-17RC." (PMID 37270497, 2023). "After systemic IL-17A blockade, the expression of those inflammatory mediators (IL36G, S100A8, DEFB4A, and DEFB4B) was decreased in posttreatment psoriasis lesional skin KCs compared to pretreatment psoriasis lesional skin KCs (p < 0.05)." (PMID 37781383, 2023). "Mice lacking adiponectin develop severe psoriasis-like dermatitis and elevated levels of the Th17-related cytokines IL-17A, IL-17F, and IL-22." (PMID 36675592, 2023). "Interestingly, targeting IL-17A itself was initially developed for IBD but resulted in exacerbated symptoms, and the approach has since then proven safe and effective for treating psoriasis and psoriatic arthritis." (PMID 38567051, 2023). "In addition, systemic anti-IL-17A monoclonal antibody administration promotes regulatory DCs, while strongly downregulating the expression of IL23A in dendritic cells in psoriasis skin lesions." (PMID 37781383, 2023). "Likewise, keratinocyte expression of CERS6 was decreased after incubation with TNF and IL-17A, which also mimicked the downregulation of CERS6 in psoriasis lesional skin." (PMID 35900871, 2022). "Also, myeloid cells are important producers of TNF-α, iNOS, and IL-23, which promote the production of IL-17A by CD4+ T cells, and contribute to cardiovascular comorbidities related to psoriasis." (PMID 36741386, 2022). "In the case of our patients, blocking IL-17A or the receptor unit IL-17-RA failed to control psoriasis." (PMID 36614836, 2022). "IL-17A levels were significantly lower in patients with moderate-to-severe psoriasis and CVD than in those without CVD." (PMID 35008981, 2022). "Accordingly, CMTM4-deficient mice had a severe defect in the recruitment of immune cells following IL-17A administration and were largely resistant to experimental psoriasis, but not to experimental autoimmune encephalomyelitis." (PMID 36271145, 2022). "IL-17-producing T helper (Th17) cells, which produce IL-17A, IL-17F, IL-21, and TNF-α, are involved in the pathogenesis of various autoimmune diseases, including RA, multiple sclerosis, and psoriasis." (PMID 35148758, 2022). "IL-17A, IL-22, and IFN-γ can promote the abnormal proliferation of keratinocytes to form a positive feedback loop and continuously aggravate the inflammatory response of psoriasis." (PMID 35966027, 2022). "The key role of IL-17A in psoriasis has been proved by the upregulation of IL-17A and related genes in affected and non-affected skin of psoriatics and secretion of IL-17A by cells involved in psoriasis pathogenesis." (PMID 36226313, 2022). "We showed here the abundance of IL-17A mRNA and protein expression by blood neutrophils isolated from psoriasis patients with and without keratinocyte stimulation and by neutrophils from healthy controls only under the situation of keratinocyte stimulation." (PMID 35401573, 2022). "With elevated production of IL-17A by γδ T cells in the serum of psoriasis patients, GLS1-mediated glutaminolysis could promote psoriasis by inducing differentiation of Th17 and γδ Th17 cells." (PMID 36211442, 2022). "After four weeks of adalimumab treatment, we showed that there was no decrease in protein levels of IL-17A and IL-17F or their receptors in synovium and skin in our cohort of PsA patients with mild psoriasis." (PMID 35203534, 2022).
psoriasis (continued). "Taken together, these results indicate that treatment of IL-17A in our self-assembled RSE model reproduces the macroscopic and histological phenotype of psoriasis and our self-assembled RSE model demonstrates disease-specific characteristics within a 3D structure." (PMID 35745784, 2022). "Serum Claudin-1 (but not IL-17A) levels show a highly significant difference (p = 0.008) between early-onset and late-onset psoriasis patients." (PMID 35340911, 2022). "PASI did not correlate significantly with either IL-17A or Claudin-1 in psoriasis and their subtypes." (PMID 35340911, 2022). "Of considerable interest, the correlation matrix revealed a distinct cytokine panel where cytokines (IFN-γ, IL-18, TNF-α, IL-12B, IL-17A, IL-17F, and IL-22) were positively correlated with each other in psoriasis patients but not in healthy controls." (PMID 36118416, 2022). "Local administration of NG-anti-miR-210 could significantly down-regulate miR-210 expression, reduce the mRNA level of IL-17A and INF-γ, and alleviate the skin lesion symptoms of psoriasis." (PMID 36618400, 2022). "The available biologics for psoriasis basically target the function of TNF-α, IL-17A orIL-12/23 includes etanercept (anti-TNF receptor fusion protein), adalimumab and infliximab (anti-TNFα antibodies), anti-IL-17(receptor) molecules and ustekinumab." (PMID 36518145, 2022). "However, in combination with IL-17A and other cytokines, TNF-α is a significant element of the cytokine milieu in psoriasis." (PMID 35313642, 2022). "Intriguingly, IL-17A is not present in PsO cytokine signature, whereas IL-17A is one of the main cytokines that drives cutaneous inflammation in psoriasis." (PMID 36426370, 2022). "IL-17C is the most abundant IL-17 isoform in lesional psoriasis skin, shares 27% homology with IL-17A and is produced by epithelial cells rather than hematopoietic cells that produce the other IL-17 family members." (PMID 35008981, 2022). "This study revealed that topical administration of astilbin at a lower dose targeted the TLR7/8 signalling pathway, subsequently inhibiting Th17/IL‐17A‐induced immune responses and excessive keratinocyte proliferation to ameliorate IMQ‐induced psoriasis‐like skin lesions in SKH‐1 mice." (PMID 35023281, 2022). "In psoriasis, YAP signaling is activated by IL-17A, promoting keratinocyte proliferation." (PMID 36276287, 2022). "Results showed that this preparation can improve psoriasis symptoms by down-regulating the expression of IL-17A, Ki67, and CD4+T. This experiment provides great scalability for researchers to treat psoriasis, avoid first-pass effects, and increase the concentration of targeted drugs." (PMID 35409158, 2022). "Because our psoriatic skin model is induced by IL-17A alone, it only recapitulates some part of the psoriasis pathogenesis, not all the aspects." (PMID 35745784, 2022). "Although it was reported that IL-17 levels increase with increasing disease severity, there are not enough studies examining the relationship between serum IL-17A levels and the severity of psoriasis." (PMID 33356031, 2021). "Imiquimod (IMQ)-induced psoriasis model is widely used in fundamental research, but it’s not able to accurately show anti-psoriatic effect of IL17A antagonists with conventional modelling condition." (PMID 33509093, 2021). "In addition, IL-23 promoted the expression of IL-17A, IL-17F, IFN-γ, and IL-22 in M0 macrophages, and IL-23-treated M0 macrophages significantly enhanced psoriasis-like dermatitis in the mouse model." (PMID 33681365, 2021). "Yet another recent report showed that treatment with IL-17A inhibitors in severe psoriasis did not significantly change body composition parameters such as body mass (median baseline BMI was constant at 32.8 kg/m2)." (PMID 34947847, 2021).
psoriasis (continued). "Mixed cytokines, including IL-17A, IL-22, oncostatin M, IL-1α, and TNF-α (M5), were used to simulate HaCaT keratinocytes to establish a psoriatic keratinocyte model that generates some phenotypic features in common psoriasis in vitro." (PMID 34202301, 2021). "There are reports indicating that IL17A pathway is not the only determinant in IMQ-induced mice psoriasis, we assumed that pathological change induced by 62.5 mg of IMQ was too severe to be protected by antibody." (PMID 33509093, 2021). "However, the group with mild psoriasis (BSA ≤ 20 and DLQI ≤ 10) demonstrated higher levels of expression of IL-17A and IL-17RA." (PMID 34945130, 2021). "Psoriasis is a hyperproliferative skin disease with a predominant Th1/Th17 response, with an upregulated concentration of multitude cytokines (TNF-α, IL-1β, IL-12, IL-17A, IL-22, IL-23, interferon-γ, and IL-13)." (PMID 34685480, 2021). "Notably, mRNA expression level of IL-38 was negatively related to psoriasis area and severity index (PASI) and IL-17A, but positively correlated with cytokeratin 10 (CK10) expression." (PMID 34539413, 2021). "Mixed cytokines, including IL-17A, IL-22, oncostatin M, IL-1α, and TNF-α (M5), are used to simulate HaCaT keratinocytes in vitro to establish a psoriatic keratinocyte model that generates some common phenotypic features of psoriasis." (PMID 34202301, 2021). "Treatment with LEU, but not VER and HP extract improved psoriasis-related inflammation via suppression of the PI3K/AKT signaling in IFN-γ/IL-17A/IL-22-stimulated HaCaT cells." (PMID 34834106, 2021). "Mechanically, glycyrrhizin inhibits the expression of STAT3 by reversing the inhibitory effect of IL-17A on SIRT1, which may be a potential mechanism by which glycyrrhizin improves psoriasis." (PMID 34044769, 2021). "Therefore, this study involved the use of IL-17A/IL-22/IFN-γ/TNF-α–induced HaCaT cells and mice with IMQ-induced psoriasis." (PMID 34456715, 2021). "Likewise, previous data from our group described the increased induction of IL-9, IL-17A and IFN-γ by CLA+CD4+ T cells after C. albicans activation in four psoriasis patients compared to healthy individuals." (PMID 33546306, 2021). "However, the expression of IL-17A in skin lesions of the P group was higher than in N and C groups on FMT-4d, with no statistical difference, accompanied by the recovery of the psoriasis-like phenotype." (PMID 34881280, 2021). "Previous studies report a positive correlation between IL-17A and psoriasis severity, but they assessed IL-17A protein level in serum or tissue, not gene expression." (PMID 34945130, 2021). "In psoriasis patients, IL17C mRNA is upregulated and expression of IL-17C increased compared to non-lesional or healthy skin; indeed, keratinocytes produce IL-17C in much higher amounts than IL-17A." (PMID 34201664, 2021). "Although these two isoforms are equally expressed in ACT1D10N/D10 fibroblasts, ACT1D10N/D10 T cell expressed predominantly ACT-D10N, leading to a dysregulated hyperactive TH17 response with elevated IL-17A and IL-22 expression in ACT1D10N/D10 T cells and consequently severe psoriasis." (PMID 34777377, 2021). "This fact explains the higher detection of IL-17A in G1, G2 and G4, which was not seen in the topical treatment group (G3) with mild psoriasis." (PMID 34068473, 2021). "Therefore we probed into illustrating the exact role of IL17A and its signaling in IMQ-induced psoriasis progression." (PMID 33509093, 2021). "In summary, glycyrrhizin may reduce the secretion of IL-17A through the SIRT1-STAT3-IL-17A pathway in TH17 cells and keratinocytes in vivo, thereby weakening the regulation of IL-17A in other cells and improving psoriasis." (PMID 34044769, 2021). "Although using IMQ model in IL17A antagonist evaluation is not throughout investigated, the participation of IL17A in the model of IMQ-induced psoriasis has been reported by several studies." (PMID 33509093, 2021).
psoriasis (continued). "Furthermore, the ELISA data showed that the pro-inflammatory mediators including IL-6, IL-17A, IL-23, IL-24, and TNF dramatically increased in psoriasis-like mice intervened by shLuc." (PMID 34638757, 2021). "Therefore, we used RT-PCR to assess the mRNA levels of inflammatory cytokines, such as IL-6, TNF-α, IL-17A, and IL-17F, in skin tissues of mice with IMQ-induced psoriasis." (PMID 33995368, 2021). "In vivo studies showed that PSORI-CM02 markedly reduced angiogenesis in the skin of mice with IMQ-induced psoriasis, while significantly rebalancing antioxidant/oxidant levels; inhibiting the production of IL-6, TNF-α, IL-17A, and IL-17F; and repressing the synthesis of angiogenic mediators." (PMID 33995368, 2021). "The coculture of CLA+ T cells activated with S. pyogenes clearly demonstrated that non-treated guttate psoriasis patients produced significantly more IL-17A/F cytokines than IFN-γ." (PMID 34778294, 2021). "The importance of IL-17F in psoriasis development became more evident in mice lacking Il17f gene, which exhibited a more pronounced decrease in acanthosis than mice lacking Il17a." (PMID 34201664, 2021). "Cytokines such as IFN-γ, IL-17A or IL-22 bind to cell surface receptors and the signal transduction occurs through JAKs, which in turn promotes STAT1 and/or STAT3 phosphorylation and activation in psoriasis." (PMID 33986690, 2021). "Additionally, Vγ9Vδ2 T cells have been shown to produce psoriasis-relevant cytokines, such as IFN-γ, TNF-α, and IL-17A and chemokines such as IL-8, CCL3, CCL4, CCL5, and CCR6." (PMID 33732249, 2021). "In the lesional skin of patients with psoriasis, TRM consist of both CD4 and CD8 fractions, which synchronize the elevated immune response by the increased expression of inflammatory cytokines, such as IL-17A, IL-22, and IFN-γ." (PMID 34501272, 2021). "Interleukin-17A (IL17A) is a proinflammatory cytokine critically involved in autoimmune diseases, and monoclonal antibodies of IL17A have been approved for clinical treatment of psoriasis." (PMID 33509093, 2021). "Moreover, CD8αα+T cells produce higher levels of IL‐17A and IFN‐γ than CD8αβ+T cells, both in peripheral blood of patients with psoriasis and healthy controls." (PMID 35663772, 2021). "Previous studies demonstrated that the pro-inflammatory cytokines, including TNF-α, IL-6, IL-1β, IL-17A, and IL-22 were up-regulated in psoriatic skin tissues and serum, and the IL-23/IL-17 axis was found to participate in the regulation of IMQ-induced psoriasis-like skin inflammation." (PMID 32515468, 2020). "IL-17A affects, in particular, keratinocyte immune function, by inducing the release of antimicrobial peptides and chemokines, such as CXCL8/IL-8 and CXCL1/GRO-α, responsible for the accumulation of neutrophils in the early phase of psoriasis inflammation." (PMID 32352958, 2020). "Furthermore, Cl-amidine-treated Il36rn−/− mice with psoriasis-like lesions showed decreased TNF-α, CXCL1, IL-1β, IL-36γ, and IL-17A expression compared to those in untreated, IMQ-induced Il36rn−/− mice." (PMID 33214582, 2020). "The Wnt signaling pathway in osteocytes and osteoblasts was blocked in a mouse model of psoriasis, which was mediated by the action of IL-17A, leading to arrest of bone formation in vivo rather than activation of osteoclast formation." (PMID 32708317, 2020). "Further, the concentration of serum IL-17A in psoriasis patients was not significantly different when compared with levels in healthy controls." (PMID 32382290, 2020). "In this study, we explored several factors that contributed to psoriasis, such as TNF-α, IL-17A, and IL-22 and found that chrysin could ameliorate the inflammatory reactions induced by these factors." (PMID 32076123, 2020). "In addition, real-time RT-PCR analysis showed that IL-1β, IL-17A, IL-36γ, CXCL1, and CXCL2 expression was increased in IMQ-induced psoriasis-like lesions in Il36rn−/− mice." (PMID 33214582, 2020).
psoriasis (continued). "IL-17A also upregulated CCL20 production via EGFR activation and further potentiated scratch-induced CCL20 production, suggesting that epidermal CCL20 production is an integral part in the pathogenesis of psoriasis and Koebnerization." (PMID 31936670, 2020). "The mixture of IL-17A, IL-22, oncostatin M, IL-1α, and TNF-α (M5) cytokines were used to simulate HaCaT keratinocytes to establish psoriatic keratinocyte model recapitulating some features of psoriasis in vitro." (PMID 33081840, 2020). "While IL-17A was a well known marker, KLK-7 represented a novel psoriasis plasma biomarker." (PMID 31953524, 2020). "We determined the mRNA expression levels of several inflammatory cytokines that are important in psoriasis (TNF-α, IL-23p19, IL-17A, IL-22, IFN-α, IL-1β, IL-6, and IL-10) and a chemokine that promotes the migration of neutrophils (CXCL2) using quantitative real-time PCR." (PMID 32752186, 2020). "These experimental models indicate that IL-17A induces psoriasis-like lesions in a dose-dependent manner, irrespective of its cellular source." (PMID 32070069, 2020). "The levels of cytokines IL-17A, IL-23, and TNF-α were significantly higher in the IMQ groups, which could reflect the pro-inflammatory status in the psoriasis mouse model." (PMID 31956331, 2020). "In the future, development of an IL-17A vaccine may provide a novel therapeutic strategy to treat SLE and other autoimmune disorders, such as rheumatoid arthritis, spondyloarthritis, and psoriasis." (PMID 32059488, 2020). "In our clinical study in psoriasis patients, the cells with TRM markers were increased in the active skin lesion and decreased after the systemic treatment with anti-IL-17A mAb, although they were relatively resistance to the treatment compared to the non-TRM cells." (PMID 33633737, 2020). "Th17 cells exert an effect by secreting IL-17A, IL-17F, IL-26, and TNF in psoriasis, forming a feedforward inflammatory network with KCs, activating STAT-1 and NF-κB signaling pathway, and inducing keratinocytes (KCs) to secrete several pro-inflammatory factors." (PMID 32377228, 2020). "A synthetic ADAMTSL5 peptide increases the frequency of CD8 T cells expressing IL17A and IFNɤ among the peripheral blood mononuclear cells in psoriasis patients, but the same effect is not found in healthy individuals." (PMID 33050592, 2020). "The presence of psoriasis did not appear to influence the choice of TNFi in this cohort, which was largely recruited prior to the introduction and wide-spread use of IL-17A inhibitors." (PMID 32641447, 2020). "The molecular basis of interleukin (IL)‐17A in driving psoriasis pathogenesis is not fully elucidated yet." (PMID 32173900, 2020). "In addition, TNF-α, CXCL1, IL-1β, IL-17A, and IL-36γ mRNA expression levels in IMQ-induced psoriasis-like lesions were significantly reduced by Cl-amidine administration compared to those in vehicle-treated Il36rn−/− mice." (PMID 33214582, 2020). "That the tumor necrosis factor-α (TNF-α) and IL-23/IL-17A axes appear to be major drivers in the pathogenesis of psoriasis is underscored by the excellent response of psoriasis to biologics targeting TNF-α, IL-23, and IL-17A, although a difference exists in their efficacy." (PMID 32070069, 2020). "The cytokine network in psoriasis has been proven by the therapeutic effectiveness of biologic antibodies that block individual cytokines, including TNF-α, IL-23/IL-12p40, anti-IL-23p19, IL-17A, and IL-17 receptor." (PMID 33633737, 2020). "Other studies have shown that Langerin‐DTR mice could reduce the inflammation of psoriasis‐like dermatitis induced by IMQ and reduce the number of γδT cells produced by permeable IL‐17A." (PMID 32916775, 2020). "Groups that have been treated with Dysidea avara methanolic extracts are most active in reducing symptoms of induced psoriasis by decreasing amounts of IL-22, IL-17A, TNF-α, and decreasing neutrophils” infiltration into the epidermis, which is important in psoriasis’s pathogenesis." (PMID 33253155, 2020).